ATP6AP2 (ATPase H+ transporting accessory protein 2)
Diseases named in the same sentence as ATP6AP2 in open-access papers (continued):
Sharing a sentence is not in itself a finding about the gene and the disease.
tumor (15 papers, 2016 to 2025). "Notably, ATP6AP2 knock-in significantly decreases the relative abundance of Lachnospiraceae_NK4A136 genus, which is known to be positively associated with anti-tumor immune factors, intestinal barrier-related factors, and anti-inflammatory response." (PMID 36597142, 2023). "In light of the high frequency of ATP6AP1 and ATP6AP2 inactivating mutations in GCTs, which suggests a putative tumor suppressor role for these genes, we hypothesized that their loss of function would result in the acquisition of oncogenic properties in vitro in GCT-relevant cell models." (PMID 30166553, 2018). "As tumor cells in G1 NETs express high levels of ATP6AP2, optimal levels of ATP6AP2 suppression are expected to target NET cells without having any critical adverse effects in other cell types." (PMID 37286698, 2023). "In agreement with previous findings, we found that ATP6AP2 expression is higher in tumor tissues than that in normal tissues, moreover, level of ATP6AP2 expression in GBM is positively correlated with those of CTNNB1, CCND1 and AGT." (PMID 32143717, 2020). "To further analyze related information in big data, we have compared the levels of ATP6AP2 transcripts in tumor tissues of GBM and normal matched tissues, based on the data provided in the TCGA and GTEx databases." (PMID 32143717, 2020). "In consistence with our previous findings, the results showed that ATP6AP2 expression is higher in tumor tissues than that in normal tissues, moreover, level of ATP6AP2 transcripts in COAD is positively correlated with those of LRP6, CTNNB1, MYC, CCND1 and AXIN2." (PMID 32143717, 2020). "We have analyzed related information in the TCGA and GTEx databases and found that the ATP6AP2 transcripts in tumor tissues of either lung adenocarcinoma (LUAD) or lung squamous cell carcinoma (LUSC) are slightly higher than those of the corresponding normal tissues." (PMID 32143717, 2020). "We showed that ATP6AP2 knockdown or CD47 blockade alone inhibited tumorigenicity of SW620 and DLD1 in mice, and a combination of ATP6AP2 knockdown and CD47 blockade elicited a strong inhibition of tumor growth and development." (PMID 33603751, 2020). "Moreover, we observed a positive correlation between ATP6AP2 and CD8+ T cell tumor immune infiltration through the analysis of the Tumor Immune Estimation Resource (TIMER) database." (PMID 37993606, 2023). "On the other hand, in some patients with nonfunctioning NETs, in which the Ki67 index was greater than 10%, there were few cells stained for ATP6AP2, showing that the expression of ATP6AP2 was negatively correlated with tumor growth in nonfunctioning NETs." (PMID 37286698, 2023). "Moreover, several studies have shown that ATP6AP2 interacts with transforming growth factor (TGF)-β1 and Wnt/β-catenin molecules, which regulate the biology process during embryonic development, stem cell differentiation, and tumor formation." (PMID 37993606, 2023).
neurological disease (3 papers, 2009 to 2021). "Of note, de novo ATP6AP2 deletion variants have also been described in neurological disease, altering neuronal development, LC3b abundance and lysosomal function when modelled in the mouse and human stem cell-derived neurons." (PMID 33340069, 2021). "ATP6AP2 ((P)RR) has been reported to be involved in neuronal development and in neurogenesis and to be associated with neurological disorders, but no previous study had clarified its role in the neurogenesis fate of hADSCs and its relation with CLR-Ms." (PMID 29751779, 2018).
infection (2 papers, 2020 to 2023). The state of being infected such as from the introduction of a foreign agent such as serum, vaccine, antigenic substance or organism. "To confirm the role of ATP6AP2 in placentation, we created placental-specific ATP6AP2 deficient mice via lentiviral infection of an ATP6AP2 shRNA specifically within the trophectoderm layer of mouse blastocysts." (PMID 37588662, 2023). "Consequently, we chose to knock down the key component of V-ATPase, ATP6AP2, to assess EV-A71 infection." (PMID 32276428, 2020).
retinopathy (2 papers, 2011 to 2022). "Furthermore, Atp6ap2-deficient retinas exhibited reduced revascularization in an oxygen-induced retinopathy model." (PMID 35998033, 2022).
neurodevelopmental disorder (1 paper, 2022). A behavioral and cognitive disorder with onset during the developmental period that involves impaired or aberrant development of intellectual, motor, or social functions. "Mutations in ANKRD11, ATP6AP2 and PRPS1 have also been associated with several neurodevelopmental disorders with ID in humans." (PMID 36551904, 2022).
ATP6AP2 also shares sentences with these, for which no sentence is quoted: Hypertension (24 papers); cardiovascular disease (8); pancreatic ductal adenocarcinoma (7); Nephropathy (6); epilepsy (5); glomerulosclerosis (5); neurodegenerative disease (4); preeclampsia (4); chronic kidney disease (3); Hypercholesterolemia (3); acute kidney injury (2); Alzheimer disease (2); atherosclerosis (2); dyslipidemia (2); endothelial dysfunction (2); fibrosis (2); hepatopathy (2); Hyperglycaemia (2); Myocardial fibrosis (2); nephrotic syndrome (2); pancreatic adenocarcinoma (2); Polyuria (2); primary aldosteronism (2); prostate carcinoma (2); sarcopenia (2); type 2 diabetes (2); adenocarcinoma (1); alcoholic cardiomyopathy (1); Arts syndrome (1); cardiac hypertrophy (1).
A further 49 diseases each share a sentence with ATP6AP2 in 1 paper.